GRIA2 (glutamate ionotropic receptor AMPA type subunit 2)
Description:
Ionotropic glutamate receptor that functions as a ligand-gated cation channel, gated by L-glutamate and glutamatergic agonists such as alpha-amino-3-hydroxy-5-methyl-4-isoxazolepropionic acid (AMPA), quisqualic acid, and kainic acid. L-glutamate acts as an excitatory neurotransmitter at many synapses in the central nervous system and plays an important role in fast excitatory synaptic transmission. Binding of the excitatory neurotransmitter L-glutamate induces a conformation change, leading to the opening of the cation channel, and thereby converts the chemical signal to an electrical impulse upon entry of monovalent and divalent cations such as sodium and calcium. The receptor then desensitizes rapidly and enters in a transient inactive state, characterized by the presence of bound agonist (By similarity). In the presence of CACNG4 or CACNG7 or CACNG8, shows resensitization which is characterized by a delayed accumulation of current flux upon continued application of L-glutamate (By similarity). Through complex formation with NSG1, GRIP1 and STX12 controls the intracellular fate of AMPAR and the endosomal sorting of the GRIA2 subunit toward recycling and membrane targeting (By similarity).
Synonyms: GluR-2; GluA2; GLUR2; GLURB; GluR-K2; GluR-B; HBGR2; NEDLIB
Tractability: Small molecule: an approved drug acts on it; a structure with a bound ligand is known; a high-quality ligand is known; it has a high-quality binding pocket; it belongs to a druggable protein family. Antibody: UniProt places it where antibodies can reach, with high confidence; its Gene Ontology location is reachable by antibodies, with high confidence; UniProt predicts a signal peptide or a membrane-spanning region. PROTAC: UniProt records ubiquitination sites on it; its protein half-life has been measured; a small molecule that binds it is known.
Target class: Ligand-gated ion channel; Ionotropic glutamate receptor; AMPA receptor; Ion channel
Gene: Protein-coding gene on chromosome 4 (157,204,182 to 157,387,146, forward strand). Ensembl gene ENSG00000120251.
Subcellular location: Cell membrane; Postsynaptic cell membrane; Postsynaptic density membrane
Pathways (Reactome):
Neuronal System: Activation of AMPA receptors; Long-term potentiation; Trafficking of GluR2-containing AMPA receptors; Unblocking of NMDA receptors, glutamate binding and activation
Gene Ontology:
Molecular function: glutamate-gated receptor activity; protein binding; AMPA glutamate receptor activity; amyloid-beta binding; ligand-gated monoatomic cation channel activity; transmitter-gated monoatomic ion channel activity involved in regulation of postsynaptic membrane potential; ligand-gated monoatomic ion channel activity; monoatomic ion channel activity; signaling receptor activity
Biological process: ionotropic glutamate receptor signaling pathway; modulation of chemical synaptic transmission; synaptic transmission, glutamatergic; monoatomic cation transmembrane transport; monoatomic ion transmembrane transport; monoatomic ion transport; regulation of postsynaptic membrane potential
Cellular component: plasma membrane; postsynaptic membrane; AMPA glutamate receptor complex; asymmetric synapse; dendrite; dendritic spine; endocytic vesicle membrane; excitatory synapse; external side of plasma membrane; neuronal cell body; postsynapse; postsynaptic density; postsynaptic density membrane; postsynaptic endocytic zone; Schaffer collateral - CA1 synapse; membrane
Genetic constraint (gnomAD): Loss-of-function variants: 3 observed, 51.74 expected, observed/expected ratio (o/e) 0.058, 90% interval 0.025 to 0.15. The upper end of that interval is the gene's LOEUF score, 0.15, which puts it in group 1 of 6, group 1 being the genes least tolerant of losing a copy. Missense variants: 299 observed, 695.16 expected, observed/expected ratio (o/e) 0.43, 90% interval 0.39 to 0.47. Synonymous variants: 250 observed, 260.51 expected, observed/expected ratio (o/e) 0.96, 90% interval 0.87 to 1.07.
Gene-disease validity (ClinGen):
ClinGen rates the evidence that GRIA2 causes each of these diseases.
neurodevelopmental disorder with language impairment and behavioral abnormalities (autosomal dominant): Definitive.
Homologues: Orthologues: dog GRIA2 (99% identical), mouse Gria2 (99% identical), chimpanzee GRIA2 (99% identical), macaque GRIA2 (99% identical), pig GRIA2 (99% identical), rabbit GRIA2 (99% identical), guinea pig GRIA2 (99% identical), rat Gria2 (99% identical), tropical clawed frog gria2 (94% identical), zebrafish gria2b (84% identical), zebrafish gria2a (83% identical), Drosophila melanogaster GluRIB (45% identical), and 38 more. Paralogues in human: GRIA4 (71% identical), GRIA3 (70% identical), GRIA1 (69% identical), GRIK2 (39% identical), GRIK1 (38% identical), GRIK3 (38% identical), GRIK4 (34% identical), GRIK5 (34% identical), GRID1 (28% identical), GRID2 (27% identical), GRIN1 (25% identical), GRIN2C (22% identical), and 5 more.
Diseases named in the same sentence as GRIA2 in open-access papers:
GRIA2 is named in the same sentence as 136 diseases in open-access papers, as found by Europe PMC text mining. Sharing a sentence is not in itself a finding about the gene and the disease. The quoted sentences say what the papers report.
epilepsy (41 papers, 2013 to 2026). A brain disorder characterized by episodes of abnormally increased neuronal discharge resulting in transient episodes of sensory or motor neurological dysfunction, or psychic dysfunction. "Here, we identify a novel, heterozygous de novo pathogenic missense mutation in GRIA2 (c.1928 C>T, p.A643V, NM_001083619.1) in a 1‐year‐old boy with epilepsy, developmental delay, and failure to thrive." (PMID 36161652, 2022). "To date, 27 de novo GRIA2 variants have been identified in 31 patients with epilepsy, intellectual disability, neurodevelopmental disorders, and autism spectrum disorder." (PMID 36161652, 2022). "Mice defective for either Gria2 mRNA expression or its editing exhibit detrimental phenotypes in synaptic function, development, and behavior and disruption of Gria2 function is associated with neurological disorders such as cerebral ischemia, amyotrophic lateral sclerosis, pain, and epilepsy." (PMID 32753528, 2020). "Interestingly, the predicted targets of cluster 5 include the gamma-aminobutyric acid B receptor 2 (Gabbra2), the galanin receptor 1 (GalR1) and the glutamate receptor ionotropic AMPA 2 (Gria2), all genes whose products are implicated in the regulation of excitability and in epilepsy." (PMID 26382856, 2015). "Our patient exhibited several features previously reported for others with GRIA2 disorder, including the onset of neurological symptoms at ~6 months, epilepsy, and developmental delay." (PMID 36161652, 2022). "Genetically engineered mice that carry an editing resistant Q/R site in Gria2—with 70% GluA2 mRNA expression from wild-type and 75% editing vs. 100% in wild-type—develop severe epilepsy with generalized seizures and premature postnatal lethality." (PMID 27932948, 2016). "Losmapimod treatment could reverse NMDAR and AMPAR (specifically GRIA2) expressions, which indicated that losmapimod may protect against epilepsy through regulating synaptic protein distribution." (PMID 31231220, 2019). "The analysis identified several transcription factor binding sites, including CCAAT/enhancer-binding protein beta (C/EBP beta) and the Glucocorticoid Receptor (GR), which was previously shown to localize in Gria2 positive cells in the hippocampus and this colocalization was affected by epilepsy." (PMID 24098468, 2013). "Finally, we use our analysis to prioritize new candidate genes for epilepsy (i.e. ANK2, CACNA1E, CACNA2D3, GRIA2, DLG4) for further validation." (PMID 33441621, 2021).
schizophrenia (21 papers, 2013 to 2025). A major psychotic disorder characterized by abnormalities in the perception or expression of reality. "The promoter of GRIA2 methylates in schizophrenia, and mutations in GRIA2 cause childhood-onset schizophrenia." (PMID 36979479, 2023). "A very recent report by Alkelai and colleagues describes a young girl affected by childhood onset schizophrenia bearing a de novo stop GRIA2 variant (p.Glu508Ter)." (PMID 34768579, 2021). "In our study, we selected two SNPs distributed in GRIN1 and GRIA2 genes and tested their effects on the causality connections and structural characteristics of the frontal-striatum-thalamus pathway in Han Chinese schizophrenia patients." (PMID 32372910, 2020). "The T/T genotype of GRIA2 was reported as a low-risk genetic marker of paranoid schizophrenia." (PMID 37860710, 2023). "For example, in human hippocampal neurons, schizophrenia patients had less overall Gria2 than controls, suggesting that differences in AMPAR subunit transcription could contribute to the disease." (PMID 36936507, 2023). "In the hippocampus, subjects with CAMK2A expression < 0.79 and (at the same time) with GRIA2 expression < 0.64 achieved 95% chance of having the schizophrenia whereas those with CAMK2A expression ≥ 0.79 and EAAT2 ≥ 37 % were more likely to do not have the disease at all (probability of 0%)." (PMID 35217646, 2022). "The hypo-function of GRIN1 and GRIA2 subunits from glutamic receptors has been hypothesized as a primary process in the pathophysiology of schizophrenia." (PMID 32372910, 2020). "Moreover, editing levels of GRIA2 were previously reported to be altered in postmortem brains from schizophrenia patients." (PMID 33067431, 2020). "The hypofunction of GRIN1 and GRIA2 subunits from glutamic receptors has been hypothesized as the primary process in the etiology of schizophrenia." (PMID 32372910, 2020). "While the candidate genes used to construct this network were selected using evidence for disease implication derived from two different approaches, the network includes many additional genes of potential relevance to schizophrenia (e.g., GRIA2, GRIN1, GRIN2B, HOMER1, PICK1, and SNAP25)." (PMID 25484875, 2014). "The molecules that mostly contributed to discriminate schizophrenia from controls were EAAT2, CAMK2A, Synapsin-1, l-Asn, GRIA2, GRIA4, and SLC17A7 whereas the ones that barely contributed to the discrimination were: Gly, mGluR5, CaMKIIα, VGluT1, and d-Asp." (PMID 35217646, 2022). "We selected two loci of rs11146020 and rs3813296 distributed in GRIN1 and GRIA2 genes and tested their main and interaction effects on causality connections and structural characteristics in the frontal-striatum-thalamus pathway in 55 Han Chinese first-episode negative schizophrenia patients." (PMID 32372910, 2020). "This was accompanied by the downregulation of miR-181b target genes with an implication in schizophrenia development, including VSNL1, a member of the visinin/recoverin subfamily of neuronal calcium sensor proteins, and the glutamate receptor GRIA2, which is involved in synaptic plasticity." (PMID 32764320, 2020).
amyotrophic lateral sclerosis (20 papers, 2009 to 2025). Amyotrophic lateral sclerosis (ALS) is a neurodegenerative disease characterized by progressive muscular paralysis reflecting degeneration of motor neurons in the primary motor cortex, corticospinal tracts, brainstem and spinal cord. "Downregulation of ADAR2 caused insufficient editing of GRIA2, leading to the death of motor neurons of sporadic amyotrophic lateral sclerosis patients." (PMID 35406793, 2022). "One example that supports this hypothesis is perturbed A-to-I editing of the mRNA encoding the GRIA2 subunit of glutamate AMPA receptors which manifests in the disease amyotrophic lateral sclerosis (ALS)." (PMID 25916332, 2015). "In this case, 4 out of 5 genes from FOSB pathway were mapped to the 2 diseases: CDK5 and GRIA2 to amyotrophic lateral sclerosis and, FOSB and PPP1R1B to drug-induced dyskinesia." (PMID 19194489, 2009). "Lack of GRIA2 RNA editing is lethal in mice and impaired GRIA2 editing may associated with amyotrophic lateral sclerosis (ALS) aetiology." (PMID 34882682, 2021). "In amyotrophic lateral sclerosis (ALS), alterations in editing levels of GRIA2 and other transcripts may contribute to the disease." (PMID 33376192, 2021).
glioma (20 papers, 2009 to 2025). A benign or malignant brain and spinal cord tumor that arises from glial cells (astrocytes, oligodendrocytes, ependymal cells). "Co-expression analysis revealed that in LGG, NDUFA6-DT exhibits a positive correlation with PHLPP2 and GRIA2, known for inhibiting glioma progression." (PMID 38674418, 2024). "In disparity, Gria2 expression was down-regulated in high-grade glioma inhibiting thereby tumor cell proliferation and further inducing apoptosis." (PMID 35263365, 2022). "Under-editing of glutamate ionotropic receptor AMPA type subunit 2 (GRIA2) has been reported to play a role in glioma aggressive phenotype." (PMID 33062411, 2020). "For analysis relationship between the Q607R editing level and ADAR family expression level in glioma samples, we first calculated the editing level of Q607R site in GRIA2 based on CGGA RNAseq database." (PMID 30524204, 2018). "In contrast, GRIA2 expression is lost in high-grade glioma and forced expression in glioma cells inhibited proliferation and induced apoptosis." (PMID 25326682, 2014). "Interestingly, among the genes that we found to be up-regulated in the HD-type, a few like GRIA2, BCAN and LPAR4 were already shown to be directly or indirectly implicated with glioma cell invasion." (PMID 22901239, 2012). "An alternative scheme is that ADAR3 facilitates the alternative splicing of the GRIA2 pre-mRNA transcript, hence providing another method of preventing ADAR2 editing to promote glioma proliferation and malignant progression." (PMID 32375856, 2020). "In support of this interpretation, Miat was found to regulate the NGS gene Gria2 in transgenic mouse MB, but MIAT (the human orthologue of Miat) was found not to regulate any NGS genes in these glioma datasets." (PMID 37693314, 2023). "In particular, noncanonical Wnt signaling (WNT5A-FZD3) might promote glioma invasion and glutamatergic signaling ((SLC1A3 + GLS)–GRIA2) is known to stimulate tumor cells growth, proliferation, and survival." (PMID 38499808, 2024).
depression (19 papers, 2009 to 2025). "Molecular docking demonstrated a superior binding affinity between glycine and GRIA2, suggesting that metabolites might play an important role by influencing receptor proteins in the treatment of depression." (PMID 38694223, 2024). "Furthermore, GNAO1 is closely related to epileptic encephalopathy and neurological dysfunction, PRKCB exerts a regulatory effect on neuronal function, and GRIA2 is closely related to status epilepticus and depression." (PMID 36533076, 2022).
glioblastoma (19 papers, 2009 to 2025). The most malignant astrocytic tumor (WHO grade IV). "While GRIA2 transcripts are normally subjected to RNA editing by ADAR2, decreased editing of GRIA2 transcripts in glioblastoma is associated with downregulation for ADAR2 and altered GluA2 function." (PMID 38493171, 2024). "As it is devoid of A-to-I editing functionality, ADAR3 mediates its effect on cancer by inhibiting RNA editing, mostly notably that of ADAR2-mediated glutamate receptor ionotropic AMPA2 (GRIA2) A-to-I editing (glutamine-to-arginine substitution at residue 607) in glioma and glioblastoma." (PMID 39126156, 2025). "In particular, a comparative study reported that ADAR3 could compete with ADAR2 for binding to glutamate receptor ionotropic AMPA 2 (GRIA2) mRNA, inhibiting ADAR2-catalyzed A-to-I editing at the Q/R site of GRIA2 in glioblastoma." (PMID 40483535, 2025). "However, ADAR3 also regulates CSC proliferation in glioblastoma by directly competing with ADAR2 at the editing site of GRIA2 to inhibit ADAR2." (PMID 37853437, 2023). "In glioblastoma, ADAR2-catalyzed A-to-I conversion activates GRIA2 mRNA to promote CSC proliferation." (PMID 37853437, 2023). "As additional target for glioma progression was identified in the GRIA2 transcript which is edited by ADAR2, where less editing at the Q/R site enhances glioblastoma invasion through activation of the Akt pathway." (PMID 26437436, 2015). "Although in these studies neurons were shown to be the site of editing of AMPA receptor subunit, monocytic cells isolated from glioblastomas have also known to express and upregulate the expression of GRIA2 (GluA2 or AMPA receptor 2)." (PMID 26834738, 2015). "Overall, these data indicate the essential role of ADAR2 editing in glioblastoma, acting on multiple targets (CDC14B, pri-miR-221/222, pri-miR-21, miR-376a-5p, GRIA2) that together contribute to varying extents to cancer progression." (PMID 26437436, 2015). "To sum up, we identified seven genes (GRIA1, GRIA2, GRIK1, GRIK4, GRM3, GLUL, BCAT1) whose mRNA expression may serve as potential molecular biomarker candidates to distinguish glioblastoma and brain metastases tissue derived from surgical resections." (PMID 38835368, 2024).
Alzheimer disease (17 papers, 2009 to 2025). A progressive, neurodegenerative disease characterized by loss of function and death of nerve cells in several areas of the brain leading to loss of cognitive function such as memory and language.
Anxiety (12 papers, 2015 to 2025). Intense feelings of nervousness, tension, or panic often arise in response to interpersonal stresses. "Reductions in AMPAR transmission have been implicated in anxiety and stress, while disruption in the trafficking of the GRIA2 subunit has been associated with predisposition to stress." (PMID 35888164, 2022).
Intellectual disability (10 papers, 2019 to 2024). "GRIA2 human mutations have been associated with neurodevelopmental abnormalities, including intellectual disability, autism spectrum disorder, seizures, and developmental epileptic encephalopathy." (PMID 38227384, 2024). "Pathogenic variants of GRIA1–4 have been described in patients with developmental delay, intellectual disability, autism spectrum disorder, and seizures, with GRIA2 variants typically causing AMPAR loss of function." (PMID 36161652, 2022). "Indeed, heterozygous de novo GRIA2 mutations cause intellectual disability and neurodevelopmental abnormalities including autism spectrum disorder, Rett syndrome-like features, and seizures or developmental epileptic encephalopathy." (PMID 32781725, 2020). "A genetic deletion that includes the GRIA2 gene encoding GluA2 is associated with autism and mutations of RAB39B that cause intellectual disability comorbid with autism lead to impaired transport of GluA2 to synapses and subsequent shift of AMPAR to higher calcium permeability." (PMID 30800064, 2019). "Here, we report heterozygous de novo GRIA2 mutations in 28 unrelated patients with intellectual disability (ID) and neurodevelopmental abnormalities including autism spectrum disorder (ASD), Rett syndrome-like features, and seizures or developmental epileptic encephalopathy (DEE)." (PMID 31300657, 2019).
status epilepticus (8 papers, 2016 to 2025). Status epilepticus is defined as a continuous seizure lasting more than 30 min, or two or more seizures without full recovery of consciousness between any of them. "We also validated the screening phenotype for GRIA2, an AMPA receptor subunit that is downregulated after kainate-induced status epilepticus in the hippocampus." (PMID 39990495, 2025).